GZMA (granzyme A)
Diseases named in the same sentence as GZMA in open-access papers (continued):
Sharing a sentence is not in itself a finding about the gene and the disease.
cancer (continued). "As a comprehensive pan-cancer exploration, we next investigated the impact of DNA methylation of GZMA, GZMB, GZMK and PRF1 on survival outcomes." (PMID 40002821, 2025). "These collectively emphasize GZMA’s potential as a pivotal biomarker and restorative target in cancer, advertising a point-by-point understanding of its expression scene and suggestions for persistent forecasting and treatment procedures." (PMID 39228516, 2024). "GSDMB, which shows increased expression in inflammatory diseases and certain cancers, can be activated by granzyme A secreted by immune cells." (PMID 39735183, 2024). "The cytolytic activity (CYT) score is a new index of cancer immunity calculated from the mRNA expression levels of GZMA and PRF1, representing immune cytotoxicity." (PMID 38438381, 2024). "Our study delved into the expression and immune infiltration characteristics of the GZMA gene in pan cancer cells, revealing its abnormal expression in tumors and closely related to various immune cells." (PMID 39228516, 2024). "We have used the probes for real‐time imaging of active GzmA secreted by reinvigorated human NK‐92 cells (compound 9) and antigen‐driven recognition of mouse CTLs in co‐cultures with cancer cells (compound 10)." (PMID 36562327, 2023). "CTLs and NK cells secrete granzyme A (GzmA) upon recognition of cancer cells; however, there are very few tools that can detect physiological levels of active GzmA with high spatiotemporal resolution." (PMID 36562327, 2023). "Other important biomarkers involve the secretion of proteolytic enzymes (e.g., GzmA and GzmB), which are key effector molecules in cytotoxic T cells and can be used for real-time monitoring of anti-cancer immunotherapy efficacy." (PMID 37376918, 2023). "At the gene-level, the cytolytic granzyme A (GZMA) and K (GZMK) enzyme, CD8A and the chemokine CXCL10 illustrious of T and NK-cells and the testis antigen SPAG5 were associated with infiltration to cancer tissue." (PMID 37391505, 2023). "When the GSDMB pore-forming N-terminal domain is released by Granzyme-A cleavage, it provokes cancer cell death, but uncleaved GSDMB promotes multiple pro-tumoral effects (invasion, metastasis, and drug resistance)." (PMID 36899106, 2023). "Previous studies have highlighted the importance of GZMA as a key effector molecule in regulatory T-cell function within the context of cancer." (PMID 37760494, 2023). "Studies have shown that NK EVs contain perforin, granzyme A, granzyme B, granulysin, and FasL, proteins that activate both intrinsic and extrinsic apoptosis pathways in cancer cells." (PMID 37818374, 2023). "The GZMA was identified as CD8 + T cell co-expression genes that promoted infiltration of CD8 + T cells in an antigen presentation process of cancer." (PMID 37620327, 2023). "CDKN2A displayed higher mutation rates across multiple cancer types (31%), and other frequently mutated genes included LRPPRC (13%), PRKAA2 (11%), VLDLR (9%), ASNS (8%), GZMA (7%), GLS (7%), TNFRSF1A (6%), PSAT1 (5%), and PRDX6 (4%)." (PMID 37534256, 2023). "Expression of MLL3 or MLL4 is also negatively associated with GZMA, GZMB, and IFNG mRNA levels in a variety of human cancer types, highlighting increased immune cytotoxicity towards MLL3- and MLL4-low tumors." (PMID 36323669, 2022). "Recently, studies have found that granzyme proteases, such as GzmA and GzmB, can induce pyroptosis of cancer cells by cleaving GSDM family members." (PMID 36523974, 2022). "Heterologous overexpression of GZMA-cleavable human GSDMB in mouse cancer cells accelerates the elimination of tumors in vivo." (PMID 35673561, 2022). "GSDMB-mediated pyroptosis can function downstream of GZMA, and cytotoxic lymphocytes can transmit GZMA to GSDMB-expressing cancer cells, enhancing antitumor immunity." (PMID 35739182, 2022). "More recently, it has been shown that GzmA cleaves Gasdermin B (GSDMB) to trigger pyroptosis of target cancer cells." (PMID 34413857, 2021).
cancer (continued). "In contrast to exposure to mf, exposure to cancer cell lines increased the phagocytic ability of monocytes and reduced their ability to induce T cell proliferation and to expand Granzyme A+ CD8+ T cells." (PMID 29668679, 2018). "We next performed Kaplan–Meier survival analysis on 37 TCGA-datasets deriving from 25 different cancer types in order to estimate the risk of individual and/or simultaneous high (or low) PRF1 and GZMA expression on patient overall survival." (PMID 29515971, 2018). "We found that higher local immune activity (as measured by the mRNA levels of Granzyme A and Perforin-1) predicted smaller expression noise in cancers." (PMID 27713130, 2016). "The results suggested that CD4 T cells expressing GZMA are of ability to anti-cancer." (PMID 40959273, 2025). "Additionally, alterations in GZMA methylation levels were linked to survival disparities in ACC and SKCM, further emphasizing the potential prognostic implications of DNA methylation in the context of GZMA across diverse cancer types." (PMID 40002821, 2025). "The cytolytic activity (CYT) score is a new index of cancer immunity calculated from the mRNA expression levels of GZMA and PRF1; we concluded that the HCC patients with higher ICRPI had lower CYT scores compared to those observed in lower ICRPI patients (p < 0.01)." (PMID 36611994, 2023). "In this sense, we can speculate that during immunocyte attack, released NE might preferentially trigger CD95-dependent apoptosis in cancer cells and counteract GZMA-mediated pyroptosis." (PMID 36899106, 2023). "So, whether the GZMA can kill cancer cells through pyroptosis also depends on the expression of GSDMB, which do not express in some human tissue and is absent in mouse." (PMID 35673561, 2022). "Taken together, these findings not only demonstrated that GSDMB-mediated pyroptosis acts downstream of GzmA but that cytotoxic lymphocytes may deliver GzmA into GSDMB-expressing cancer cells to facilitate antitumor immunity." (PMID 34429144, 2021). "Finally, IDO1 and the cytotoxic molecules including GZMA and PRF1 showed a positively stronger association with GMFG in most cancer types." (PMID 33863293, 2021). "Granzyme A and B are serine proteases, which are secreted together with perforin from cytotoxic T cells and natural killer cells, and are involved in eliminating cancer cells and cells infected with viruses and bacteria by inducing programmed cell death." (PMID 33168626, 2021). "It has been reported that natural killer (NK) cells and cytotoxic T lymphocytes could kill cancer cells by releasing granzyme A (GZMA) to cleave GSDMB and granzyme B (GZMB) to directly cleave GSDME to activate pyroptosis in cancer cells." (PMID 34616734, 2021). "Finally, we found that IDO1 and the cytotoxic molecules including PRF1 and GZMA had a positive correlation with the PD-1 in most cancer types." (PMID 30607140, 2018). "CTL/NK cells can kill cancer cells by overexpressing GZMA and PRF1." (PMID 29515971, 2018). "This investigation highlighted the diverse associations between DNA methylation of GZMA, GZMB, GZMK, and PRF1 and survival outcomes, displaying the potential prognostic implications of epigenetic modifications in immune-related genes across different cancer types." (PMID 40002821, 2025). "In addition to 5, cell impermeable qABP 6, which retains excellent reactivity and selectivity for GzmA, may be well positioned for specifically studying extracellular roles of GzmA in the context of inflammation and cancer." (PMID 41258732, 2025). "Additionally, the lack of STAT5 also downregulated the expression of key effector molecules, such as perforin, granzyme A/B, and IFN-γ, which might account for the poor cytotoxic performance of STAT5-deficient NK cells against cancer cell lines." (PMID 39872864, 2024). "Some studies suggest that GZMA could be a potential target for cancer therapy." (PMID 39228516, 2024).
cancer (continued). "In addition, it was recently found that the serine protease granzyme A (GZMA) in cytotoxic lymphocytes could access target cells via perforin and evoke cancer cells to undergo pyroptosis by cleaving activated GSDMB protein, as well as activate immune response." (PMID 35847844, 2022). "Additionally, it has been demonstrated that NK and CD8+ T cells can induce pyroptosis in cancer cells that express GSDMB to promote tumor clearance via the GzmA-GSDMB axis, moreover, this process is enhanced by interferon-γ (IFN-γ) and tumor necrosis factor (TNF)." (PMID 36523974, 2022). "To determine the prognostic implications of GZMA, GZMB, GZMK and PRF1 across the different cancer types, we explored their Kaplan–Meier plots." (PMID 40002821, 2025). "External validation yielded a 4-gene set (GZMK, GZMA, ITGAL, and IL7R); higher gene expression levels predicted better overall survival in The Cancer Genome Atlas cohort (p=0.005)." (PMID 40766148, 2025). "In summary, the CNV analysis of GZMA, GZMB, GZMK and PRF1 across multiple cancer types highlighted a remarkable prevalence of heterozygous amplifications and deletions compared to homozygous variations." (PMID 40002821, 2025). "In conclusion, our study underscores the multifactorial impact of GZMA, GZMB, GZMK and PRF1 and their potential as biomarkers for personalized cancer immunotherapy." (PMID 40002821, 2025). "Our findings align with those of recent studies emphasizing the significance of immune-related genes, specifically GZMA, GZMB, GZMK and PRF1, in cancer pathogenesis and clinical outcomes." (PMID 40002821, 2025). "An increasing number of studies have found that GZMA, derived from cytotoxic T lymphocytes, cleaves GSDMB, leading to the formation of pores on the cell membrane and inducing pyroptosis in cancer cells expressing GSDMB." (PMID 39735183, 2024). "It is indicative that the expression levels of both CYT markers (GZMA and PRF1) can predict the favorable prognosis of cancer patients who receive ICI therapy." (PMID 38612436, 2024). "CYT is closely related with patient prognosis and outcomes and the expressions of both GZMA and PRF1 genes synergistically, or alone can affect the OS of cancer patients." (PMID 38612436, 2024). "Herein, we rationally designed fluorogenic probes to detect physiological levels of active GzmA in mouse and human cells and tissues, and to image CTL reinvigoration against cancer cells in real time." (PMID 36562327, 2023). "In a context of immune activation, NK and T-cells secrete GZMA, which in turn cleaves GSDMB either at the K229 or K244 residues within cancer cells, inducing pyroptosis and the subsequent antitumoral immune response." (PMID 36899106, 2023). "Significantly upregulated PRGs included PYCARD in 12 cancers; GSDMB in 10 cancers; IL18 in 9 cancers; GSDMD, CASP8, GZMB, and GPX4 in 8 cancers; AIM2 and CASP6 in 7 cancers; GZMA in 6 cancers; GSDME, CASP4 and DHX9 in 5 cancers; GSDMA and GSDMC in 4 cancers." (PMID 36605187, 2022). "Further analysis revealed a significant decrease in antitumor factors (GZMA, GZMB, NKG7, and PRF1) in CD8T cells and an increase in the proportion of cancer cells, especially in the cancer-cell-dominant group." (PMID 36497182, 2022). "In order to better understand the role of GZMA-F2R communication in HCC, the GZMA and F2R RNA-seq data from 33 cancer types and nine HCC datasets were analyzed." (PMID 35256589, 2022). "Recently, it has been revealed that lymphocyte-derived Granzyme-A can cleave GSDMB within tumor cells, thus provoking a pyroptotic cancer cell death." (PMID 36163066, 2022). "Partially because the methods are optimized for different cancer types, the overlap between genes used in the TMEPRE model and genes used in the TIDE model is small (IL21R, GZMA)." (PMID 34594218, 2021).
cancer (continued). "In human cancer cell lines endogenously expressing GSDMB, specifically OE19 (esophageal carcinoma), SW837 (CRC), and SKCO1 (CRC), it was further shown that GzmA delivery through electroporation or perforin was sufficient to induce GSDMB-mediated pyroptosis." (PMID 34429144, 2021). "GSDMB is specifically cleaved by lymphocyte-derived GZMA, unleashing its pore-forming activity and inducing pyroptosis in GSDMB-expressing cancer cells." (PMID 33941231, 2021). "Specifically, the mRNA expression levels of both granzyme A (GZMA) and perforin (PRF1) have been reported to be novel indicators of CYT cancer immunity." (PMID 34193146, 2021). "For example, lymphocyte-derived granzyme A (GZMA) cleaves gasdermin B (GSDMB) at the linker, which unleashes its pore-forming activity and results in pyroptotic cell death of GSDMB-expressing cancer cells." (PMID 33941231, 2021). "The antitumoral immune cytolytic activity (CYT), calculated from the mRNA expression of granzyme A (GZMA) and perforin 1 (PRF1), is a relatively new indicator of cancer immunity." (PMID 34316699, 2021). "In line with their synchronized roles, the expression of GZMA and PRF1 was strongly coordinated across the different cancer samples (Spearman rank correlation, rho = 0.87)." (PMID 29515971, 2018). "Among the genes that we found down-regulated are: GZMA, GZMB, HLA-A, -B, -C and IFNG, all supporting a model of impaired CD8 T cell cytotoxic activities, one of the most important anti-cancer responses." (PMID 29928478, 2018). "Protein expression profiles of granzyme A (GZMA) and perforin 1 (PRF1) across 19 different cancer types, using antibody-based protein profiling data from immunohistochemistry (the Human Protein Atlas)." (PMID 29515971, 2018). "Additionally, we collected the IC50 values of drugs from various cancers and cell lines from the GDSC and CTRP databases in order to correlate them with GZMA, GZMB, GZMK and PRF1 expression levels." (PMID 40002821, 2025). "Similarly, we observed that across multiple cancer types, OTUB2 expression was negatively correlated with the expression of the CTL signature genes GZMB, GZMA and CD69." (PMID 38167274, 2024). "Intratumoral immune cytolytic activity (CYT), calculated as the geometric mean of granzyme-A (GZMA) and perforin-1 (PRF1) expression, has emerged as a critical factor in cancer immunotherapy, with significant implications for patient prognosis and treatment outcomes." (PMID 38612436, 2024). "Immune checkpoint inhibitors (ICIs) act specifically to block CTLA4 and PD-1, so we compared GzmA and GzmB expression in CD57+ CD4+ T cells in blood obtained from cancer patients before and after treatment with anti-CTLA4/PD-1 (ipilimumab/nivolumab) combination checkpoint inhibitor therapy." (PMID 37161048, 2023). "Hemicyanine fluorophores have been described for targeting different biomolecules and enzymes, but there are no examples of NIR fluorescent substrates to image active GzmA resulting from the interactions between immune cells and cancer cells." (PMID 36562327, 2023). "Hypomethylation across cancers was observed for AIM2, CASP8, GZMA, and IL-1B." (PMID 36605187, 2022). "Cytotoxic immune cells such as natural killer cells and CD8+ T cells can also trigger cancer cell pyroptosis through lymphocyte-derived granzyme A (GZMA) or granzyme B (GZMB) but not caspases-mediated cleavage of the GSDM family proteins." (PMID 35432318, 2022). "Specifically, in cancer cells xenografted in immunocompetent mice, the GSDMB intrinsic pyroptotic function could be activated via immunocyte-derived Granzyme A (GZMA)." (PMID 35281099, 2022). "A third group of cancers comprised of BLCA, BRCA, UCEC, LIHC, STAD, PRAD and THCA showed a similar expression pattern with first group of cancers except for the contrast behavior of NLRP3, NLRC4, PRF1, CASP1, CASP4, and GZMA (downregulated in this group)." (PMID 36605187, 2022).
cancer (continued). "The CAFDL signature was significantly positively associated with TGFB1, CD276, CD40, VEGFA, VEGFB, etc., but showed significantly negative correlation with immune checkpoints (such as CD274, PDCD1, CTLA4, TIGHT, and HAVCR2) and anti-cancer immune regulators (IFNG, IDO1, and GZMA)." (PMID 35967425, 2022). "In one study quantitating immune cytolytic activity based on the expression level of the CD8 T cell cytolytic effector molecules granzyme A (GZMA) and perforin (PRF1), ccRCC ranked highest among 15 cancer types, and the scoring was markedly increased compared to pRCC and benign renal tissue." (PMID 34831452, 2021). "We first explored whether RE neoantigen burden might be associated with somatic neoantigen burden, expression of the immune markers including GZMA/PRF1/PD1, cytolitic activity (CYT), and clinical covariates in different cancer types." (PMID 33363023, 2020). "Also of notice, a pronounced number of critical immunomodulators, which were described in an immunogenomic analysis of major TCGA cancer data sets and included PDCD1LG2, BTN3A2, GZMA, BTLA, CD28, ICOS, and IDO1, were contained in the 358 DEG set." (PMID 32603365, 2020). "Studies in humans and NHP have shown that IPP- or HMBPP-activated Vγ2Vδ2 T cells can readily produce Th1 cytokines IFN-γ/TNF-α and cytotoxic granule molecules perforin (PRF), granzyme A/B (GZMA/B), and granulysin (GNLY), and consistently exhibit antimicrobial and anti-cancer activities." (PMID 31080452, 2019). "Interestingly, CD4+ Texterm phenotype exhibited the highest expression of cytotoxic markers (PRF1, GZMA, GZMB, IFNG, and GNLY), aligning with recent discoveries indicating that cytotoxic CD4+ T cells within tumors can directly kill cancer cells." (PMID 40335494, 2025). "Notably, the GZMA CD4 T cell subset exhibited elevated expression of genes associated with effector and cytolytic functions in CD4 T cells, including GZMA, GZMH, GZMM, and PRDM1, while also showing moderate expression of anti-cancer-related genes such as IFNG, PRF1, and TNFSF10." (PMID 40959273, 2025). "Therefore, the ability of GZMA to induce pyroptosis and kill cancer cells also depends on the expression of GSDMB, which is not expressed in some human tissues and is absent in mice." (PMID 39735183, 2024). "The killing of cancer cells by CD8+ T cells and NK cells purified from the same mice was also markedly reduced, and the reduced granzyme activity was reflected in the slower turnover of model peptide substrates specific to granzyme A (GzmA) and granzyme B (GzmB)." (PMID 39021839, 2024). "Moreover, our data may prove useful in the field of cancer research, as the roles of SPINK1 in EGFR binding and granzyme A inhibition are still poorly understood." (PMID 35408828, 2022). "Interestingly, the expression levels of the cytotoxic effectors PRF1, GNLY, GZMA, GZMB and GZMH in CD8+ Tex subclusters were even richer than those in CD8+ Teff subclusters, which implied that CD8+ Tex cells still tended to respond to cancer cells." (PMID 35562760, 2022). "Thus, an extensive analysis of GZMA, GZMB, GZMK and PRF1 may not only provide a greater understanding of their role in cancer biology, but also reveal their similarities and differences across different cancer types." (PMID 40002821, 2025). "In addition, our current understanding of the complete roles of GZMA, GZMB, GZMK and PRF1 are still evolving and other factors may play a role in the varying expression levels of these genes in the context of the different clinical prognoses seen in these cancer types." (PMID 40002821, 2025). "Proteases present in malignant tumours but not in normal skin included: PGC, BAP1, caspase-8, F13A1, MMP11, MMP23, MMP25, MMP26 and granzyme-A." (PMID 35327667, 2022). "Moreover, Granzyme A (GZMA) and Perforin 1 (PRF1), which have been validated as surrogates of immune activity in cancer, were not expressed in either dataset." (PMID 31383035, 2019).
cancer (continued). "However, responders had an increase in CD8, GZMA and PRF1 expression levels compared to non-responders, implying that cytolytic T lymphocytes with high cytotoxic activity were strongly infiltrated, expanded, and activated in cancer tissues by dual blockade in responders and TNBC patients." (PMID 29721177, 2018).